Y_RNA (Y RNA )
Gene: Miscellaneous RNA gene on chromosome 7 (75,325,959 to 75,326,060, reverse strand). Ensembl gene ENSG00000202021.
Homologues: Orthologues: chimpanzee Y_RNA (99% identical), pig Y_RNA (75% identical). Paralogues in human: Y_RNA (100% identical), Y_RNA (97% identical), Y_RNA (93% identical), Y_RNA (92% identical), Y_RNA (90% identical), Y_RNA (89% identical), Y_RNA (87% identical), Y_RNA (85% identical), RNY3 (84% identical), RNY3P12 (84% identical), Y_RNA (84% identical), RNY3P1 (83% identical), and 98 more.